MMP9 (matrix metallopeptidase 9)
Diseases named in the same sentence as MMP9 in open-access papers (continued):
Sharing a sentence is not in itself a finding about the gene and the disease.
diabetes (continued). "MMP-9 expression was significantly higher in diabetic rat retinas compared to controls at all time points.TIMP-1 expression was nonsignificantly upregulated at 1week of diabetes and was significantly downregulated at 4 and 12 weeks of diabetes." (PMID 23671886, 2013). "Moreover, deletion of uPAR blocked diabetes-induced BRB breakdown and activation of MMP-9 in mice." (PMID 23951261, 2013). "Recently, several studies documented that MMP-9 expression is regulated by extracellular-signal-regulated kinases- (ERK-) dependent pathways and in the retina RAF protooncogene serine/threonine-protein kinase- (Raf-) mitogen-activated protein kinase kinase (MEK)-ERK cascade is activated by diabetes." (PMID 23671886, 2013). "However, rosiglitazone treatment decreased MMP-9 plasma levels in patients with CAD and diabetes." (PMID 22716287, 2012). "Consequently, a refined selection comprising seven genes (MMP2, MMP9, IL17A, IL10, FGF2, IL6 and VEGFA) and eleven pharmacological agents has emerged, exhibiting promise in delivering therapeutic effects aimed at mitigating the occurrence of OP in individuals afflicted with diabetes." (PMID 38250601, 2024). "Furthermore, our previous work has shown that in diabetes, MMP-9 transcription is regulated by dynamic DNA methylation; although the activation of Dnmt increases its binding, concurrent activation of the hydroxymethylation machinery keeps the MMP-9 promoter hypomethylated." (PMID 32150828, 2020). "A decrease in Timp1 fails to properly interact with increased levels of MMP-9 and aggravates MMP-9 activation, producing a synergistic effect for an already compromised retinal vasculature in diabetes." (PMID 32150828, 2020). "But, other risk factors such as gender, smoking or addiction, hyperlipidemia and diabetes, did not influence blood levels of IL-18, MPO and MMP-9." (PMID 31516856, 2019). "In another report, because the ratio of MMP-9 and TIMP-1 is positively correlated with poor healing foot ulcers in patients with diabetes, we surmise that the issue is not high expression of MMP-9 but an inadequate ratio of MMP-9 and TIMP-1." (PMID 25884474, 2015). "Since patients with diabetes had higher MMP9 levels and higher NAS values, this study could not safely rule out that presence of diabetes influences MMP9 concentrations." (PMID 36609276, 2023). "Furthermore, we also found TAA patients tended to have higher levels of MMP9 than AAA subjects in the overall comparison, and in the non-diabetes, non-hyperlipidemia and aortic diameter ≥ 5.5 cm subgroup analysis." (PMID 30373522, 2018). "Moreover, MMP9 levels were significantly higher in TAA group than those in AAA group in the total comparison, and this discrepancy was also found in the non-diabetes, non-hyperlipidemia and aortic diameter ≥ 5.5 cm subgroup analysis." (PMID 30373522, 2018). "Also, the triple model (which includes: sofa, diabetes and TIMP1/MMP9 ratio at the first, fourth, and eighth day, does not indicate the AUC of the predictive model, it only shows the AUC of TIMP1/MMP9 ratio, which are not as significant (<70%)." (PMID 28192449, 2017).
hepatocellular carcinoma (303 papers, 2008 to 2026). A malignant tumor that arises from hepatocytes. "One study shows that a significant decrease in MMP-9 expression and secretion by HSCs in fibrotic tissue is associated with hepatocellular carcinoma." (PMID 40362835, 2025). "Using tissue immunofluorescence studies, we also report that the expression of MMP-9 is significantly decreased in activated HSCs in fibrotic tissues associated with hepatocellular carcinoma." (PMID 31086224, 2019). "Knockdown of HOTAIR was associated with reduced expression of VEGF and MMP-9 in BEL7402 hepatocellular carcinoma cells." (PMID 25405331, 2015). "Gen suppresses the enzymatic activity of matrix metalloproteinase (MMP)-9; however, the mechanism underlying its anti-invasive activity on hepatocellular carcinoma (HCC) cells is unclear." (PMID 24433534, 2014). "Knockdown of metastasis-associated in colon cancer 1(MACC1) expression using shRNA reduced hepatocellular carcinoma Huh7 cell migration and invasion abilities, which were associated with the downregulation of MMP-9 protein." (PMID 24476461, 2014). "One study reported that MMP9 could distinguish patients at risk of progression from non-alcoholic steatohepatitis to hepatocellular carcinoma." (PMID 39064719, 2024). "Recently, MTFP1 has also been implicated in promoting the migratory ability of adipose-derived stem cells as well as MMP9 expression and cancer metastasis in hepatocellular carcinoma although the underlying mechanisms are still unknown." (PMID 35589683, 2022). "In addition to the proliferation of cancer cells, autophagy activation has been shown to cause invasion of hepatocellular carcinoma cells by enhancing MMP-9 expression and glioblastoma cells by regulating DRAM1 and p62." (PMID 25704884, 2015). "High HOTAIR expression is a risk for recurrence after hepatectomy in hepatocellular carcinoma and may regulate the MMP9 and VEGF genes." (PMID 23936419, 2013). "In another study by Hsieh et.al, metformin inhibited the invasion of hepatocellular carcinoma through the inhibition of uPA and MMP-9 expression." (PMID 40450131, 2025). "Another isoform, hsa_circ_0003945, formed by the circularization of exons 11 and 12, functions as a ceRNA for miR-194-3p, enhancing MMP9-mediated oncogenic activity in hepatocellular carcinoma." (PMID 41194937, 2025). "SHP-1 can inhibit the expression of MMP-2 and MMP-9 protein in hepatocellular carcinoma cells related to migration.." (PMID 38644382, 2024). "Increased Six1 expression in macrophages promotes hepatocellular carcinoma growth and invasion by regulating MMP-9." (PMID 38509734, 2024). "Knockdown of ACK1 in hepatocellular carcinoma repressed, e.g., invasion and migration and downregulated MMP-9." (PMID 36979157, 2023). "The level of RUNX2 expression significantly correlates with the expression level of MMP9 in hepatocellular carcinoma." (PMID 37759525, 2023). "MMP9 has also shown promise in the stratification of prognosis and immune checkpoint treatment responsiveness in patients with hepatocellular carcinoma." (PMID 37106440, 2023). "IFITM3 promotes hepatocellular carcinoma invasion and metastasis by regulating MMP9 through p38/MAPK signaling." (PMID 38149381, 2023). "The formation of invadopodia was increased by a higher MSN level, which activated the β-catenin–MMP9 axis in hepatocellular carcinoma." (PMID 37446127, 2023).
hepatocellular carcinoma (continued). "Study showed that TANs are major source of MMP-9 in human head and neck cancer and hepatocellular carcinoma, and neutrophil-derived MMP-9 has been involved in the angiogenic switch and tumor growth." (PMID 37766868, 2023). "For example, RIG-I suppresses the migration and invasion of hepatocellular carcinoma cells by regulating MMP9 and predicts HCC patient prognosis." (PMID 35242239, 2022). "Our results suggested that the FAK/PI3K/AKT/mTOR pathway affects the activities and expressions of MMP-2 and MMP-9, further inhibiting the migration and invasion of hepatocellular carcinoma cells." (PMID 36483979, 2022). "For instance, tan IIA blocks the nuclear factor kappa-B (NF-κB) signaling pathway to inhibit the activity of MMP2 and MMP9, thereby preventing the metastasis and invasion of human hepatoma cells and hepatocellular carcinoma (HCC) cells." (PMID 36172186, 2022). "Multivariate analysis confirmed that the expression of matrix metalloproteinase 9 (MMP9) was an independent predictor of OS in hepatocellular carcinoma, which is consistent with our results." (PMID 35027925, 2022). "The results indicate that GsRb1 is a potential drug candidate with high specificity/selectivity on MMP-9 inhibition and inflammatory alleviation, especially for cardiac remodeling and hepatocellular carcinoma metastasis." (PMID 36432152, 2022). "The results reveal the potential use of Ginsenoside Rb1 for the treatment of inflammatory and MMP-9-related cardiac remodeling and metastasis of hepatocellular carcinomas." (PMID 36432152, 2022). "Ginsenoside Rb1 inhibited TNF-α-induced MMP-9 production in both H9c2 and liver carcinoma HepG-2 cells." (PMID 36432152, 2022). "The repression of AFP by HBP1 attenuated AFP effect on PTEN, MMP9 and caspase-3, thus inhibited proliferation and migration, and induced apoptosis in hepatoma cells." (PMID 33794968, 2021). "MMP2 and MMP9 are predictors of liver cancer recurrence and are highly expressed in invasive hepatocellular cancer (HCC) cells." (PMID 35011007, 2021). "Enhanced migration after Kyn/AhR interaction was observed in HCC (hepatocellular carcinoma) and the authors linked it with changes in the level of EMT markers, as well as the overexpression of MMP9." (PMID 34071442, 2021). "MMP9 was identified to mediate circ0001361-induced cell migration and invasion in bladder cancer, and miR-5692a induced tumor progression in hepatocellular carcinoma." (PMID 34067437, 2021). "In cancer, interleukins (ILs) induce neo-angiogenesis and enhance the activity of MMPs, which increases the metastatic activity as demonstrated in hepatocellular carcinoma where IL-8 and IL-17 cause MMP-2 and MMP-9 activation." (PMID 33981713, 2021). "N-benzylcantharidinamide promoted the degradation of matrix metalloproteinase-9 (MMP-9) mRNA in an antigen R-dependent manner in human hepatocellular carcinoma Hep3B cells." (PMID 33919224, 2021). "Similar higher levels of MMP-9 were reported in the serum of chronically HCV-infected patients and in HCV-infected hepatoma cells than in uninfected patients or cells, and MMP-9 displayed greater enzymatic activity." (PMID 34065048, 2021). "Mechanistically, a previous study demonstrated that BRD4 regulated MMP-9 expression through the SHH signaling pathway in hepatocellular carcinoma cells." (PMID 34421353, 2021). "For example, its overexpression upregulates matrix metallopeptidase 9 (MMP9) through the PI3K/Akt/GSK-3/Snail pathway in hepatocellular carcinoma (HCC) 15-17." (PMID 33767593, 2021). "In NSCLC cells and hepatocellular carcinoma, irradiation enhanced MMP-9 expression via the PI3K/AKT/NF-κB and the PI3K/AKT/MAPK pathway, respectively, leading to enhanced tumor cell invasiveness." (PMID 34055644, 2021). "Cav-1 expression has previously been reported to lead to activation of MMP2 and MMP9 promoting invasion in hepatocellular carcinoma cell lines and non-small lung carcinoma." (PMID 34490102, 2021).
hepatocellular carcinoma (continued). "The repression of AFP by HBP1 attenuates AFP effect on PTEN, MMP9 and caspase-3, thus inhibits proliferation and migration, and induces apoptosis response to oxidative stress in hepatoma cells." (PMID 33794968, 2021). "The progression of various types of cancer, such as bladder, breast, esophageal squamous cell carcinoma, intrahepatic cholangiocarcinoma, hepatocellular carcinoma, is driven by the up-regulation of MMP-9." (PMID 33081056, 2020). "In previous several studies, KIF18A was known to be associated with signalling pathways including Akt and metastasis‐related proteins (MMP‐7 and MMP‐9) in hepatoma cells and involved in Akt signalling pathways during human breast carcinogenesis." (PMID 32253833, 2020). "HuR also binds to the 3′-UTR of matrix metalloproteinase-9 (MMP-9) mRNA to increase the stability of MMP-9 mRNA, promote the expression of MMP-9, and increase the invasive ability of hepatocellular carcinoma Hep3B cells." (PMID 32775456, 2020). "The protein level of alpha smooth muscle (α-SMA) was reduced and several hepatocellular carcinoma-related genes such as MMP9, FoxM1 were down-regulated." (PMID 32471201, 2020). "The ATX-LPA-LPA1 signalling axis has been shown to induce MMP-9 expression in hepatocellular carcinoma (HCC)." (PMID 33050301, 2020). "A recent study shows that alternatively-activated macrophages (M2) can increase the invasion and migration of hepatocellular carcinoma by up-regulating MMP-9." (PMID 33081056, 2020). "MMP-2 is involved in CCL3-dependent cell invasion in oral squamous cell carcinoma and chondrosarcoma, whereas MMP-9 is involved in CCL3-dependent cell invasion in hepatocellular carcinoma and oral squamous cell carcinoma." (PMID 32457351, 2020). "Inhibition of β-catenin results in decreased expression of its downstream targets, MMP-9, C-Myc, and cyclin D1, which suppress cell cycle progression, cell proliferation, and metastasis in prostate cancer and hepatocellular carcinoma." (PMID 33264103, 2020). "In hepatocellular carcinoma, it was proven that the upregulation of the Nrf2 signaling pathway was correlated with the increased level of MMP9 (matrix metallopeptidase 9) and Bcl-xL (B-cell lymphoma extra large)." (PMID 31717324, 2019). "It has been revealed that exposure to WIN 55212-2 decreased markedly MMP-9 activity and expression both in hepatocellular carcinoma and non-small cell lung cancer cells." (PMID 29883990, 2019). "In hepatocellular cancer expression of MMP9 is upregulated by AKT1 and thus controlled in the opposite direction compared to breast and colorectal cancer." (PMID 31752925, 2019). "This research indicates that serum MMP-9/MMP-2 ratio is a potential biomarker of hepatitis B virus-related hepatocellular carcinoma." (PMID 30262739, 2018). "The authors observed that serum MMP-9/MMP-2 ratios in hepatitis B virus-related hepatocellular carcinoma patients were significantly higher than those of other groups (healthy carriers, chronic hepatitis patients and cirrhosis patients)." (PMID 30262739, 2018). "The expression of cell cycle-related protein (cyclin B1), invasion and metastasis-related proteins (MMP-7 and MMP-9) and Akt-related proteins in hepatoma cells was also decreased after knocking down KIF18A." (PMID 29466986, 2018). "In hepatocellular carcinoma and Wills tumor cells, the diminished expression of LRP1 in tumor cells correlated with increased levels of MMP9, probably due to loss of LRP1-mediated endocytosis." (PMID 29507659, 2018). "Herein, we investigated how Snail upregulated transcription of ZEB1 and MMP9 induced by the tumor promoter 12-O-tetradecanoyl-phorbol 13-acetate (TPA) in hepatoma cell HepG2." (PMID 29259250, 2017). "Norcantharidin (3,6-endoxohexahydrophthalic anhydride), a demethylated derivative of cantharidin downregulates MMP-9 via NFκB in hepatocellular carcinoma cells in vitro." (PMID 29112161, 2017).
hepatocellular carcinoma (continued). "For example, pterostilbene induces apoptosis and autophagy in bladder cancer cells, while it was shown to inhibit tumor cell invasion in hepatoma HepG2 cells by decreasing MMP-9 activity." (PMID 28785594, 2017). "Study has shown that TIMP-1/-2 and MMP-9 all play crucial roles in the tumor cell growth and invasion of hepatocellular carcinomas." (PMID 28767067, 2017). "Both MMP-2 and MMP-9 have been shown to be up-regulated after radiation in hepatocellular carcinoma and glioblastoma." (PMID 27835571, 2016). "AR has been shown to regulate cell migration by suppressing the nuclear factor kappa B/matrix metallopeptidase 9 pathway and further inhibiting hepatocellular carcinoma metastasis." (PMID 27023146, 2016). "In hepatocellular carcinoma it was shown that radiation enhances invasion via PI3k/Akt, NF-κB and subsequently MMP-9 activation." (PMID 27835571, 2016). "Curcumin can prevent the invasion of hepatocellular carcinoma through inhibiting the production of MMP-9." (PMID 27042656, 2016). "At 50 μM, RES inhibits TNF-α-mediated MMP-9 expression and invasion of human hepatocellular carcinoma cells." (PMID 26043036, 2015). "For example, IL–23 promotes hepatocellular carcinoma metastasis by NF-κB-upregulated MMP9 expression." (PMID 26437444, 2015). "The correlation between expression of Cezanne and MMP-9, clinicopathological/prognostic value in hepatocellular carcinoma was examined." (PMID 25638165, 2015). "High expression of MMP-2 and MMP-9 was found to be associated with time to tumor recurrence in HCC patients after surgical resection, while decrease the expression level of MMP-2 and MMP-9 resulted in the inhibition of invasion and metastatic capabilities of hepatocellular carcinoma cells." (PMID 26177288, 2015). "Additional reports claimed that radiation enhances cell invasion with MMP-9 in hepatocellular carcinoma through the PI3K/Akt/NF-κB signal transduction pathway." (PMID 26196246, 2015). "Nrf2 is a potential prognostic marker and promotes proliferation and invasion in human hepatocellular carcinoma partly through regulating expression of Bcl-xL and MMP-9." (PMID 26194347, 2015). "In this study, we demonstrated that the inhibition of HBx-induced MMP-9 activity by SNS in hepatoma cells occurs via NF-κB and AP-1 signaling." (PMID 26446078, 2015). "In this study, we, for the first time, found that NS4B and HCV induced the expression of four cancer-related NF-κB target genes, C-myc, Mcl-1, Cyclin D1 and MMP-9 by the EOR-Ca2+-ROS-NF-κB pathway in both human hepatoma cells and primary human hepatocytes." (PMID 25875501, 2015). "Over-expression of SCARA5 suppressed some malignant behaviors in hepatoma cells, and SCARA5 knockdown was associated with activation of MMP9." (PMID 24950699, 2014). "Kiroviski reported that MTAP knockdown upregulated MMP-9 expression through the accumulation of 5′-deoxy-5′-methylthioadenosine in hepatocellular carcinomas." (PMID 25426549, 2014). "Sublethal doses of radiation have been shown to induce MMP-9 expression in medulloblastoma, meningioma, and hepatocellular carcinoma." (PMID 23183822, 2012). "Expression of CD151 was found to correlate with expression of MMP9, and both correlated with poor prognosis in hepatocellular carcinoma." (PMID 22570691, 2012). "Treatment with γ-IR also enhanced invasion of hepatocellular carcinoma cell (HCC) cell lines via the PI3-Kinase/Akt/NF-κB/MMP-9 pathway." (PMID 22963683, 2012). "To elucidated this question, we examined the activities of MMP-9 in four hepatocellular carcinoma tissue samples by gelatin zymograph assay." (PMID 22546345, 2012). "Specially for hepatoma cell invasion, MMP-9 has been shown to be more likely to participate in hepatoma cell invasion than MMP-2 for its destruction of tumor capsule." (PMID 21738655, 2011).